DDR1 (discoidin domain receptor tyrosine kinase 1)
Diseases named in the same sentence as DDR1 in open-access papers (continued):
Sharing a sentence is not in itself a finding about the gene and the disease.
breast carcinoma (continued). "While the roles of collagen, DDR1 and breast cancer invasiveness have been well investigated the function of DDR1 in prostate cancer is not well understood." (PMID 32492656, 2020). "Although the reports differ in function on how DDR1 affects breast cancer migratory activities, DDR1 effects appear to be controlled by interacting partners in the cellular microenvironment." (PMID 32668815, 2020). "Foxy-5, a WNT5A peptide mimic, reduces the metastatic capacity of invasive breast cancer via epithelial discoidin domain-containing receptor 1 (DDR1), which decreases the motility and the invasive potential of breast epithelial cells." (PMID 33291655, 2020). "In the case of breast cancer, DDR1 possesses partly contradictory roles related to the specific breast cancer type, which is also reflected in this model comparing MCF-7 as an invasive ductal carcinoma with MDA-MB-231 as a model for TNBC." (PMID 32668815, 2020). "Surprisingly, DDR1 deletion in a breast cancer mouse model increases ECM deposition and promotes tumour aggressiveness and metastasis." (PMID 33037194, 2020). "Enforced overexpression of DDR1 in aggressive basal-like breast cancer cells suppressed their invasiveness in 3D culture models." (PMID 32492656, 2020). "For instance, genetic deletion of DDR1 increased pulmonary metastases in the MMTV-PyMT model of mammary carcinoma in mice." (PMID 32047176, 2020). "Low levels of DDR1 have been observed during the epithelial to mesenchymal transition (EMT) process in breast cancer." (PMID 32492656, 2020). "Previous reports demonstrated that cancer cell growth was downregulated by 3D type I collagen matrix in epithelial-like breast carcinoma cells and that this was dependent on activation of DDR1 by collagen." (PMID 32582700, 2020). "The inhibition of breast cancer cell growth induced by type I collagen 3D matrices has been previously attributed to a strong DDR1-dependent induced apoptosis." (PMID 32582700, 2020). "This suggested that MT1-MMP expression in basal-like breast carcinoma cells, in addition to a low basal level of DDR1 expression, protects these cells against collagen-induced apoptosis via DDR1 cleavage." (PMID 31130862, 2019). "In a previous study, we have examined this correlation in multiple breast cancer cell lines, by analyzing expression levels of E-cadherin, vimentin, DDR1, DDR2, MT1-MMP, and BIK mRNAs in 58 breast cancer cell lines." (PMID 31130862, 2019). "We have previously shown that DDR1 was able to initiate apoptosis in luminal-like breast carcinoma MCF-7 cells embedded in 3D type I collagen matrices." (PMID 31130862, 2019). "More recently, DDR1 ablation in vivo was reported to confer a basal-like phenotype to luminal-like breast carcinoma population and to increase their metastatic potential." (PMID 31130862, 2019). "TM4SF1 has been reported to couple with the collagen receptor tyrosine kinase DDR1 in breast cancer progression and pancreatic cancer invasion." (PMID 31142317, 2019). "TM4SF1 has been reported to interact with discoidin domain receptor 1 (DDR1) in breast cancer and in pancreatic cancer metastasis." (PMID 31142317, 2019). "Aberrant expression and activation of DDR1 have been reported in several human cancers, such aslung cancer, breast cancer, brain cancer, oral cancer and liver cancer." (PMID 31253192, 2019). "In contrast, the more mesenchymal breast cancer cell lines (E-cadherin-low and vimentin-high) were characterized by a weak DDR1 level, a high MT1-MMP, and a low BIK expression." (PMID 31130862, 2019). "We have previously shown that in 3D type I collagen matrix, DDR1 triggers a BIK-mediated apoptosis in poorly invasive luminal-like breast carcinomas cell lines." (PMID 31130862, 2019). "At the opposite of the luminal-like breast carcinoma cells, the basal-like ones express low levels of DDR1 and a high level of MT1-MMP." (PMID 31130862, 2019).
breast carcinoma (continued). "Recently, DDR1 knock-down in luminal-type MMTV-PyMT mammary tumor mouse model was shown to give rise to tumors displaying basal-type characteristics, a faster growth, and enhanced lung metastasis." (PMID 31130862, 2019). "DDR1 specific silencing reduced breast cancer cell proliferation, migration, and the activation of IR downstream signaling." (PMID 30513575, 2018). "To assess this, we analyzed a panel of 15 breast cancer cell lines for centrosome amplification and E-cadherin/DDR1 levels." (PMID 29133484, 2018). "In summary, this study demonstrates that DDR1 associates with the IR, enhances the activation of IR downstream signaling and the mitogenic and pro-invasive effects of insulin and IGF-2 in breast cancer cells." (PMID 28591735, 2017). "We first evaluated by immunoblot the expression of DDR1 and IR in a panel of human breast cancer cell lines (MCF-7, T47D, ZR-75, BT-474, MDA-MB-157, MDA-MB-231, MDA-MB-468)." (PMID 28591735, 2017). "In the present work we aimed at elucidating the biological role of the IR - DDR1 crosstalk in human breast cancer cells." (PMID 28591735, 2017). "Definitively, these computational data strongly suggested that a general positive correlation between DDR1 and IR transcripts exists in breast carcinoma." (PMID 28591735, 2017). "In a panel of breast cancer cells, DDR1 knockdown by specific siRNAs markedly inhibited IR downstream signaling as well as proliferation, migration and colony formation in response to insulin and IGF-2." (PMID 28591735, 2017). "Bioinformatics analysis of public domain databases showed that IR and DDR1 co-expression significantly correlates with several clinically relevant histopathological and molecular features of human breast carcinomas." (PMID 28591735, 2017). "Significantly, we have previously shown that IGF-1, IGF-2 and insulin induce DDR1 upregulation in breast cancer cells by activating the AKT/miR199a-5b pathway." (PMID 28591735, 2017). "Our present results demonstrate that in human breast cancer cells DDR1 is a signaling partner of the IR and a strong modulator of IR expression and biological responses." (PMID 28591735, 2017). "By analyzing publicly available databases, we found that the correlation between DDR1 and IR is stronger in breast cancer specimens than in normal breast tissues." (PMID 28591735, 2017). "In breast cancer, DDR1 accelerated cell migration through blocking the migration suppressor tyrosine-protein kinase (SYK) activity." (PMID 28743276, 2017). "According to these findings, DDR1 enhanced breast cancer cell proliferation, invasion and colony formation in response to insulin and IGF-2." (PMID 28591735, 2017). "In MCF-7 human breast cancer cells, IR and DDR1 co-immunoprecipitated and co-localized after insulin or IGF-2 stimulation." (PMID 28591735, 2017). "In our previous studies, we also demonstrated that the role of WNT5A in increased adhesion is mediated by its ability to phosphorylate DDR1, resulting in the reduced migration of breast cancer cells." (PMID 27623766, 2016). "A report indicated that overexpression of DARPP-32 in breast cancer cells that express DDR1, a receptor tyrosine kinase, significantly impaired cell migration." (PMID 26872373, 2016). "We previously showed that, in breast cancer cells, DDR1 silencing by small RNA interference impairs IGF-I induced downstream signaling and biologic responses." (PMID 26655502, 2016). "While in MDA-MB-231 breast cancer cells, DDR1 suppresses migration only when co-expressed with its interacting partners, the Dopamine and cAMP-regulated neuronal phosphoprotein-32 (DARPP-32)." (PMID 27014069, 2016). "In MDA-MB-468 breast cancer cells, DDR1-dependent promotion of cell migration was shown to be induced through a regulation of the migration suppressor tyrosine-protein kinase (SYK) activity." (PMID 27014069, 2016).
breast carcinoma (continued). "Both in breast cancer cells and transfected fibroblasts, IGF-I stimulation induced rapid tyrosine-phosphorylation of DDR1, which was accompanied by increased association of the DDR1 – IGF-IR complex, rapid internalization and sorting to early endosomes." (PMID 26655502, 2016). "Taken together, these results indicate that, in breast cancer, paracrine/autocrine IGFs are positive modulators of DDR1 expression, and help explaining the frequent DDR1 overexpression in a variety of malignancies with dysregulated IGF axis." (PMID 26655502, 2016). "Stimulation of MDA-MB-231 breast cancer cells with type IV collagen is able to induce cell migration through a DDR1 and CD9-dependent pathway." (PMID 27014069, 2016). "DDR1 silencing was accompanied by a reduction of IGF-IR protein levels in all three breast cancer cell lines tested while DDR1 overexpression was associated with enhanced IGF-IR levels, which were especially marked in MCF-7 and MDA-MB-231 cells." (PMID 25840417, 2015). "Alternatively, direct modulation of DDR1 signaling can be achieved solely by the high level of DDR1 expression in pancreatic and breast cancer models." (PMID 25369402, 2014). "In breast cancer, DDR1 was overexpressed in both primary breast tumor samples and metastasis-containing lymph nodes." (PMID 21541037, 2011). "Additionally, we found that a DDR1 signature GSVA score was positively correlated with KAT2A expression in metastases from breast cancer patients." (PMID 41826695, 2026). "Further examination of this co-occurring mutation across all cancer studies on cBioPortal showed that this mutational relationship between DDR1 and either RUNX1 or CBFβ remained strongly significant, indicating that this axis is worth investigating outside of breast cancer." (PMID 40614729, 2025). "Notably, the DDR1 extracellular domain mediated collagen fiber remodeling to restrict immune infiltration in breast cancer, while DDR1 inhibition promoted cytotoxic lymphocyte recruitment and tumor suppression." (PMID 40993737, 2025). "DDR1 facilitates migration and invasion in breast cancer cells via FAK signaling activation." (PMID 40603853, 2025). "However, it has been interestingly reported that the expression of DDR2 is elevated in breast cancer tissues compared to normal breast tissues, whereas that of DDR1 is decreased in breast cancer tissues." (PMID 39766183, 2024). "Furthermore, deletion of DDR1, a collagen activated receptor tyrosine kinase, can promote intratumoral penetration of T cells and suppress tumor growth in mouse models of breast cancer." (PMID 37709489, 2023). "We then explored whether EFL1 represses breast cancer liver metastasis by targeting DDR1-regulated immune infiltration." (PMID 37709489, 2023). "Supported that, DDR1 overexpression was found in breast cancer and inhibited T cell infiltration." (PMID 37031216, 2023). "In addition, tumor DDR1 promotes collagen fiber alignment and contributes to breast cancer development by instigating immune exclusion." (PMID 37709489, 2023). "Another study showed that targeting DDR1 with a humanized monoclonal antibody reversed immune exclusion by increasing T-cell infiltration and significantly increased antitumor efficacy in a mouse model of immunocompetent breast cancer." (PMID 38136314, 2023). "In contrast to this finding, DDR1 is a pro-apoptotic receptor in breast cancer." (PMID 36249782, 2022). "By using murine models of mammary tumor cells, they could show that DDR1 ablation prevented tumor development in immuno-competent, but not in immune-deficient mice, thus uncovering a new DDR1 function in tumor immune evasion." (PMID 35936735, 2022). "In the absence of DDR1, tumor cells exhibit a basal phenotype leading to enhanced invasion and are associated with the development of breast cancers of poor prognosis." (PMID 33917302, 2021). "IGF1, for example, induces the expression of DDR1 in breast cancer cells." (PMID 33670586, 2021).
breast carcinoma (continued). "In contrast, in other breast cancer studies, DDR1 was found to be a proapoptotic receptor." (PMID 33917302, 2021). "Notably, DDR1 enhanced breast cancer cell proliferation, migration, and colony formation in response to insulin and IGFs." (PMID 34206590, 2021). "Interestingly, a reduction in DDR1 mRNA levels was shown in most middle- to high-grade human breast carcinomas compared with normal mammary tissues." (PMID 35004699, 2021). "Interestingly, the combination of MT1-MMP depletion and DDR1 overexpression synergistically increased 3D COL1-induced apoptosis to a level similar to that observed in luminal breast carcinoma MCF-7 cells." (PMID 35004699, 2021). "In the case of breast carcinoma, in vitro inhibition of DDR1 promotes tumor growth only in 3D." (PMID 33917302, 2021). "DDR1 is highly expressed in epithelial-like breast carcinoma cells, but poorly in basal-like ones." (PMID 35004699, 2021). "The effect of DDR1 on EMT inhibition has also been demonstrated in vivo in breast cancer." (PMID 33917302, 2021). "Indeed, IGF-I receptor can phosphorylate DDR1 in breast carcinoma thus inducing co-internalization of the receptors and incorporation into early endosomes." (PMID 32582700, 2020). "However, other studies have demonstrated that, in breast carcinomas, DDR1 promotes apoptosis through induction of pro-apoptotic protein BIK1." (PMID 32582700, 2020). "Additionally, collagen I-mediated signaling through discoidin domain receptor tyrosine kinase 1 (DDR1) is a requirement for the reactivation of dormant breast cancer cells." (PMID 33022920, 2020). "DDR1 mediates MMP9 induced by native type IV collagen in MDA-MB-231 breast cancer cells." (PMID 32090682, 2020). "Notably, signaling processes initiated by DDR1 are similar to those of integrins and have recently been associated with CAM-DR in breast cancer cells." (PMID 33287446, 2020). "However, DDR1 transcript levels were barely detectable in basal-like breast cancer MDA-MB-231 cells as previously reported." (PMID 31653854, 2019). "Another possibility to explain this differential expression pattern of DDR1 between these two types of breast carcinoma could be related to a CpG methylation of the DDR1 promoter during epithelial-mesenchymal transition." (PMID 31130862, 2019). "To address this point and in order to study tumor cells harboring endogenous MT1-MMP, we investigated whether basal-like MDA-MB-231 breast carcinoma cells present a low level of DDR1 expression." (PMID 31130862, 2019). "In addition to a high level of DDR1 expression, the luminal-like breast carcinoma cells are characterized by a low expression level of MT1-MMP." (PMID 31130862, 2019). "Finally, it is important to keep in mind that despite its low expression level in the aggressive breast carcinomas, DDR1 plays also a crucial role in the proteolysis-based cell invasion of a collagen-rich stroma." (PMID 31130862, 2019). "Since DDR1 is moderately expressed in basal-like breast carcinoma cells, we propose to explore whether overexpression of DDR1 could restore apoptosis." (PMID 31130862, 2019). "DDR1 expression level was analyzed in a cohort of TCGA breast cancer patients." (PMID 31130862, 2019). "Our data suggest that, in addition to the known markers related to mesenchymal features (basal-like), the concomitant overexpression of MT1-MMP and downregulation of DDR1 expression should be considered as important biomarkers in the prognosis of breast carcinomas." (PMID 31130862, 2019). "However, although our in vitro data suggest that low level of DDR1 expression should be considered as an additional important biomarker in the prognosis of breast carcinoma, these data need to be confirmed in future animal studies." (PMID 31130862, 2019).
breast carcinoma (continued). "In conclusion, and in agreement with the other studies, our data suggest that during the acquisition of mesenchymal features, the level of full-length DDR1 expression should be considered, in addition to the other markers, as an important biomarker in the prognosis of aggressive breast carcinomas." (PMID 31130862, 2019). "In some of the basal-like breast carcinoma cells, it has been reported that the low level of DDR1 expression could be compensated by an increase in DDR2 expression." (PMID 31130862, 2019). "However, in invasive basal-like breast carcinoma cells, DDR1 has been described to promote linear invadosomes and tumor invasion." (PMID 31130862, 2019). "Thereafter, in human breast cancer cells, we confirmed that DDR1 is a signaling partner of IR-A." (PMID 30513575, 2018). "As the expression of WNT5A protein predicts longer disease-free survival in breast cancer patients, its metastasis-suppressing activity might at least in part be due to increased DDR1-dependent cell adhesion and decreased migration." (PMID 30171384, 2018). "In order to verify whether DDR1 and IR expression positively correlated in human breast cancer specimens we used a bioinformatic analysis." (PMID 28591735, 2017). "In order to evaluate whether the DDR1 and IR co-localize in breast cancer cells, MCF-7 cells were plated onto coverslips, serum-starved for 24h and stimulated with either insulin or IGF-2 at a dose of 10nM for 5 and 20 min." (PMID 28591735, 2017). "Our data strongly suggest that DDR1 might be an important determinant of IR overexpression in breast cancer." (PMID 28591735, 2017). "Flow cytometry of DDR1 showed that under standard transfection conditions used for co-expression experiments, mean DDR1 fluorescence levels were similar to those on the breast cancer cell line T47D but approximately three times higher than those on primary keratinocytes (HEK 5 μg DNA vs T47D)." (PMID 28590245, 2017). "We now evaluated whether DDR1 is able to exert a role in breast cancer biology by functionally cross-talking with IR." (PMID 28591735, 2017). "Interestingly, this cross-talk occurs also independently of the collagen binding actions of DDR1 and, in human breast cancer cells, amplifies the stimulatory biological effects of IGF-I toward proliferation, migration and colony formation." (PMID 27384677, 2016). "Indeed, transfection of breast cancer cells with miR-199a-5p markedly downregulated DDR1 protein while miR-199a-5p antagomir upregulated it." (PMID 26655502, 2016). "Interestingly, in breast cancer cells and transfected fibroblasts, DDR1 appears to be an important regulator of IGF-IR expression, trafficking and signaling, and increases the expression of IGF-IR protein, thus potentiating its biological activities." (PMID 26655502, 2016). "Indeed, in breast cancer cells, exposure to IGFs induced upregulation of DDR1 protein through a PI3K/AKT/miR-199a-5p signaling cascade." (PMID 26655502, 2016). "It was demonstrated that DDR1 associates with DARPP-32 in a protein complex, which regulates migration, and the phosphorylation of Thr-34 residue is required for DARPP-32 function to impair migration of breast cancer cells." (PMID 26872373, 2016). "Collectively, these data strongly support our in vitro data and provide strong evidence that IGF-IR activity may induce DDR1 upregulation through decrease of miR-199a-5p in vivo human breast cancer." (PMID 26655502, 2016). "Furthermore, inhibition of DDR1 in human colon carcinoma cells, breast cancer cell lines and collagen treated Hodgkin lymphoma cells resulted in an increase in cell death in response to induced DNA damage." (PMID 27014069, 2016). "Indeed, overexpression of DDR1 in Hs587T breast cancer cells reduced their in vitro migratory behavior in type I collagen three dimensional (3D) culture system." (PMID 27014069, 2016). "We therefore assessed whether DDR1 may modulate IGF-IR-induced biological responses in breast cancer cells." (PMID 25840417, 2015).